FABP6 (fatty acid binding protein 6)
Diseases named in the same sentence as FABP6 in open-access papers (continued):
Sharing a sentence is not in itself a finding about the gene and the disease.
hepatocellular carcinoma (1 paper, 2025). A malignant tumor that arises from hepatocytes. "In hepatocellular carcinoma, FABP6 is associated with bile acid metabolic reprogramming and can be included in a multi-gene model to predict sorafenib resistance." (PMID 40717587, 2025). "FABP6 is highly expressed in hepatocellular carcinoma and is significantly associated with shortened overall survival in patients." (PMID 40717587, 2025). "For example, FABP4 enhances mitochondrial β-oxidation to reduce cisplatin-induced apoptosis in ovarian cancer, while FABP5 promotes chemoresistance in hepatocellular carcinoma through the HIF-1α pathway, and FABP6 enhances CRC resistance to oxaliplatin through KLF5-dependent transcription." (PMID 40717587, 2025).
inflammatory bowel disease (1 paper, 2022). A spectrum of small and large bowel inflammatory diseases of unknown etiology. "Dysfunctions of FABP6 and SLC10A2 are mainly involved in hepatobiliary diseases, inflammatory bowel disease, metabolic diseases and intestinal tumors." (PMID 35283765, 2022).
malignant glioma (1 paper, 2021). A grade III or grade IV glioma arising from the central nervous system. "This study aimed to assess the involvement of FABP6 expression in the progression of malignant glioma." (PMID 34685761, 2021). "The results of this study show that FABP6 may be a potential therapeutic target combined with TMZ for malignant gliomas." (PMID 34685761, 2021). "The attenuation of FABP6 inhibited the migration of malignant glioma cells." (PMID 34685761, 2021). "This is the first study to investigate the role of FABP6 in malignant glioma." (PMID 34685761, 2021). "Therefore, further investigation of the role of FABP6 in malignant glioma is imperative." (PMID 34685761, 2021).
melanoma (1 paper, 2020). A malignant, usually aggressive tumor composed of atypical, neoplastic melanocytes. "The expression of CD36, MARCO, FABP4, FABP6, and FABP7 in melanoma samples and healthy skin biopsies is visualized, according to data retrieved from the IST Online database." (PMID 32209538, 2020).
Myeloma (1 paper, 2023). "Myeloma cell proliferation also decreased with genetic knockout of FABP5, although FABP signaling compensation may have occurred via upregulation of FABP6." (PMID 36880649, 2023).
prostate carcinoma (1 paper, 2016). A carcinoma that arises from epithelial cells of the prostate gland. "Why FABP6 is localised in nucleus is not known, since it is not differentially expressed between benign and malignant tissues, it is unlikely to be related to prostate cancer." (PMID 27779102, 2016).
urothelial carcinoma (1 paper, 2022). A malignant neoplasm derived from the transitional epithelium of the urinary tract (urinary bladder, ureter, urethra, or renal pelvis). "However, the role of FABP6 has not been explored in urothelial carcinoma (UC)." (PMID 35216267, 2022).
tumor (22 papers, 2018 to 2025). "ETV4 and FABP6 were co-expressed in tumor samples and significantly associated with metastasis in CRC." (PMID 33648461, 2021). "In CRC, FABP6 overexpression might be associated with early-phase carcinogenesis, as higher levels of FABP6 correlate with smaller tumour size, more frequent location in the left colon, and reduced depth of tumour invasion." (PMID 41149452, 2025). "FABP6 regulates tumor progression through ERK, JNK, and NF-κB pathways, and combined with temozolomide therapy can enhance therapeutic efficacy." (PMID 40717587, 2025). "Bladder Cancer: FABP6 promotes tumor proliferation and migration by regulating autophagy and cell cycle proteins (CDK2/4)." (PMID 40717587, 2025). "The role of FABP6 in cancer involves multiple molecular mechanisms: metabolic regulation: FABP6 affects tumor cell energy supply through bile acid transport and fatty acid metabolism." (PMID 40717587, 2025). "In tumor immune evasion, FABP6 downregulates the expression of MHC class I molecules on tumor cells, reducing recognition by cytotoxic T cells and thus escaping host immune surveillance." (PMID 40717587, 2025). "Esophageal Cancer: FABP6+ tumor cells interact with T cells through the MIF pathway, promoting immune suppression." (PMID 40717587, 2025). "Future directions entail experimentally confirming the role of FABP6 in potentiating tumor growth, metastasis, and Treg recruitment." (PMID 38277205, 2024). "Our analysis revealed that both normal epithelial cells and FABP6+ tumor cells within the tumor tissue exhibited cellular interactions with various subtypes of T cells." (PMID 38277205, 2024). "FABP6, identified as a defining marker for cluster 0, was found to be highly expressed in these tumor cells compared to normal epithelial cells." (PMID 38277205, 2024). "In GBM cells, FABP6 inhibition reversed the malignant phenotypes of tumor cells and increased TMZ sensitivity." (PMID 37830163, 2024). "Compared to FABP6+ tumor cells, normal tissues were found to lack the MIF-related pathway in our analysis of cellular communication output signal patterns." (PMID 38277205, 2024). "By identifying FABP6 as a defining marker, we can distinguish and categorize cluster 0 as a specific subset of tumor cells within the tumor microenvironment." (PMID 38277205, 2024). "Cluster 0 was characterized by high expression of FABP6, indicating a potential role in fatty acid metabolism and tumor growth." (PMID 38277205, 2024). "The characterization of tumor cell subpopulations reveals a precursor cluster with high FABP6 expression, MAPK pathway activation, and poor patient survival." (PMID 38277205, 2024). "The enrichment of transcription factors MYC and TAF7 in cluster 0, along with pathway enrichment analysis, revealed the activation of the MAPK pathway in these FABP6+ tumor cells." (PMID 38277205, 2024). "Key findings demonstrate an enrichment of FABP6-expressing tumor cells with high fatty acid metabolism, alterations in T cell infiltration patterns, and increased cellular communication between FABP6+ tumor cells and Tregs." (PMID 38277205, 2024). "Cellular communication analysis identified increased interactions between FABP6+ tumor cells and T cells, with the involvement of the MIF-related pathway and the CD74-CD44 interaction." (PMID 38277205, 2024). "Differential signaling pathways, such as CXCL and MIF-related pathways, were observed between FABP6+ tumor cells and normal tissues." (PMID 38277205, 2024). "Both normal epithelial cells and FABP6+ tumor cells exhibited cellular interactions with various T cell subtypes, highlighting the presence of communication between these cell populations." (PMID 38277205, 2024). "Inconsistent with our findings, overexpression of FABP6 in DLD-1 cells decreased the proliferation of CRC tumor cells." (PMID 36033394, 2022).
tumor (continued). "In our study, FABP6 was selected for functional study because it ranked at the top in both cold tumor vs. hot tumor group and tumor tissue vs. normal tissue group." (PMID 36033394, 2022). "The conditioned medium from tumor cells was collected after the knockdown of FABP6 for 48 h and added to the lower chamber." (PMID 36033394, 2022). "Pancancer analysis revealed that FABP6 was upregulated in most cancers, indicating its role in promoting the progression of tumor cells." (PMID 36033394, 2022). "In in vitro experiments, the proliferation, apoptosis, and migration of tumor cells were hardly altered after suppression of FABP6 expression, even though the transwell assays showed a slightly decreasing trend of migration and invasion." (PMID 36033394, 2022). "Sequentially, our study showed that the suppression of FABP6 using siRNA enhanced the immunogenicity of tumor cells." (PMID 36033394, 2022). "Analysis with the Tumor IMmune Estimation Resource (TIMER) also revealed that FABP6 expression was negatively correlated with the immune infiltration of B cells, CD8+ T cells, CD4+ T cells, macrophages, neutrophils, and DCs." (PMID 36033394, 2022). "The results suggested that knockdown of FABP6 combined with cisplatin (2.5 mg/kg) treatment remarkably suppressed tumor growth after five weeks as shown by BLI value." (PMID 35216267, 2022). "Collectively, the reduction in p-ERK, p-JNK, and p-65 impaired tumor progression in FABP6 inhibition." (PMID 34685761, 2021). "With the available TCGA data, the expression of the FABP6 gene in healthy and tumour tissue has been compared." (PMID 32640984, 2020). "On the other hand, VEGFA and FABP6 genes are overexpressed in tumour tissue, which makes them possible candidates for inhibitory therapy." (PMID 32640984, 2020). "The FABP6 gene and its role within different metabolic pathways were studied in tumour and normal tissue and we observed the capability of the FABP6 gene to be a therapeutic target." (PMID 32640984, 2020). "All of the evidence indicates that inhibition of the expression of the FABP6 gene, specifically in tumour cells, would reduce the development and growth of the tumour." (PMID 32640984, 2020). "Among the signature genes we researched, HSPA4, FABP6, S100A10, CACYBP, SHC1 and HDAC1 were associated with a higher tumor grade, CACYBP was linked with a higher clinical stage as well as T stage." (PMID 32191631, 2020). "Western blot revealed that the protein expressions of FABP4 and FABP6 were significantly higher in tumor tissues than in adjacent tissues (P < 0.001, P = 0.002, respectively)." (PMID 31651326, 2019). "Western blot revealed that the protein expressions of FABP4 and FABP6 were significantly higher in tumor tissues than in adjacent tissues." (PMID 31651326, 2019). "For example, FABP4+ LAMs release pro-inflammatory factors through lipolysis to suppress T cell function, and FABP6+ tumor cells downregulate MHC-I molecules to reduce T cell recognition, demonstrating the central role of FABPs in metabolic crosstalk between tumors and immune cells." (PMID 40717587, 2025). "The study also investigated the cellular communication between FABP6+ tumor cells and T cells." (PMID 38277205, 2024). "To gain further insights into the cellular interactions between FABP6+ tumor cells and T cells, we employed CellChat, an analysis tool, to investigate the communication patterns between FABP6+ tumor cells and T cells, with normal epithelial cells paired with T cells serving as a control group." (PMID 38277205, 2024). "The enrichment of CD74 and CD44 receptors in the tumor tissue suggests the potential interaction between FABP6+ tumor cells and Treg cells, which may contribute to immunosuppression and tumor development." (PMID 38277205, 2024). "Interestingly, we observed a significant decrease in the CXCL-related pathway in FABP6+ tumor cells compared to normal tissues." (PMID 38277205, 2024).
tumor (continued). "After conducting these analyses, we have defined cluster 0 as FABP6+ tumor cells." (PMID 38277205, 2024). "This suggests that FABP6+ tumor cells may utilize CD74 to interact with CD44 on Treg cells, potentially promoting the immunosuppressive function of Treg cells and facilitating tumor development." (PMID 38277205, 2024). "In addition, the baseline expression of FABP6 in the tumor cell lines also affects the function of knockdown and overexpression." (PMID 36033394, 2022). "In addition, our results revealed that knockdown of FABP6 increased the immunogenicity of tumor cells and promoted the secretion of immune-related chemokines, resulting in the recruitment of CD8+ T cells." (PMID 36033394, 2022). "The expression levels of FABP6 were noted in the normal and tumor tissues." (PMID 34685761, 2021). "Interestingly, in this study, immunohistochemistry and western blot analysis showed that FABP4 and FABP6 were mainly expressed in the cells from tumor tissues, and only a small amount distributed in adjacent tissues." (PMID 31651326, 2019). "This may explain why the serum levels of FABP4 and FABP6 in CRC patients cannot be completely reversed after surgical removal of tumor tissue." (PMID 31651326, 2019). "In order to further explore the specific receptors involved in the MIF pathway in FABP6+ tumor cells, we conducted an analysis and found a significant enrichment of CD74 and CD44 receptors in the tumor tissue." (PMID 38277205, 2024). "When FABP6 knockdown was combined with TMZ treatment, the tumor regressed significantly compared to the CTL group." (PMID 34685761, 2021). "The differential presence or absence of the MIF-related pathway between FABP6+ tumor cells and normal tissues highlights a potential role of MIF signaling in the tumorigenic processes associated with FABP6+ tumor cells." (PMID 38277205, 2024). "FABP6 was negatively correlated with immune infiltration, and knockdown of FABP6 increased major histocompatibility complex (MHC) class 1 expression and promoted immune-related chemokine secretion, indicating the immunogenicity enhancement of tumor cells." (PMID 36033394, 2022). "In this context, we can conclude that FABP6 is a specific biomarker for COAD and READ, so the action of an inhibitory mechanism could lead to positive results in slowing down the growth of the tumour." (PMID 32640984, 2020). "Tumor-induced secretion may only be one of the reasons for the increase of FABP4 and FABP6 in peripheral serum." (PMID 31651326, 2019). "Notably, stage-dependent correlation was observed between the expression level of two lncRNAs, lnc-FABP6-4:1 and lnc-CD164L2-1:1, and tumor grade, a grading system that characterizes level of differentiation of malignant cancer cells." (PMID 29416609, 2018). "This indicates that there is cellular communication between these cell populations, regardless of whether they originate from normal tissue or FABP6+ tumor cells within the tumor." (PMID 38277205, 2024). "FABP6 knockdown did not significantly alter tumor cell proliferation, apoptosis, and migration." (PMID 36033394, 2022). "Scratch analysis showed that knockdown of FABP6 did not affect the migration ability of tumor cells, while, interestingly, the transwell assays indicated that knockdown of FABP6 could slightly inhibit the migration and invasion compared with the control group." (PMID 36033394, 2022). "Finally, the bioluminescent images and immunostaining of MMP-2, cluster of differentiation 31 (CD31), and the VEGF receptor 1 (VEGFR1) revealed attenuated tumor progression in the combination of the FABP6-knocked-down and temozolomide (TMZ)-treated group in an orthotopic xenograft mouse tumor model." (PMID 34685761, 2021). "However, mRNA expression levels of FABP1, FABP2, FABP5, FABP6, FABP7, FABP9, or FABP12 did not significantly differ in different tumor stages in CRC patients." (PMID 34680577, 2021).
cancer (10 papers, 2016 to 2025). A tumor composed of atypical neoplastic, often pleomorphic cells that invade other tissues. "FABP6 is a cancer-associated protein that transports bile acids in ileal epithelial cells, and bile acids are known to play an important role in the development of CRC." (PMID 31651326, 2019). "Furthermore FABP6 is an early diagnostic biomarker, which would greatly assist the various possible treatments of this type of cancer." (PMID 32640984, 2020). "FABP6 plays a pro-tumorigenic role in various cancers through metabolic reprogramming, immune regulation, and activation of signaling pathways, and is a potential diagnostic biomarker and therapeutic target." (PMID 40717587, 2025). "Multiple studies have confirmed that FABP6 is an independent prognostic risk factor for CRC, HCC, and other cancers." (PMID 40717587, 2025). "Firstly, the pancancer analysis showed FABP6 was also upregulated in most cancers, indicating that FABP6 may act as a protumor factor in cancers." (PMID 36033394, 2022). "We hypothesize that FABP6 overexpression in cancer cells is linked to early-stage carcinogenesis, but it is not required for late-stage cancer progression." (PMID 34680577, 2021). "Thus, we hypothesized that FABP6 is an unfavorable prognostic biomarker in ESCA cancer." (PMID 38277205, 2024). "IHC showed nuclear staining only on BPH and carcinoma cells with antibodies to FABP6 (identified by the arrow), no cytoplasmic staining was observed." (PMID 27779102, 2016). "Although FABP6 was detected in the nucleus of the cells, the staining intensities between BPH and carcinoma tissues were not significantly different (χ2 test, p>0.08)." (PMID 27779102, 2016). "Although FABP6 was differentially expressed at the level of its mRNA, its expression at the protein level was not significantly different between the BPH and the carcinoma tissues and it was expressed in nucleus." (PMID 27779102, 2016).
infection (3 papers, 2016 to 2025). The state of being infected such as from the introduction of a foreign agent such as serum, vaccine, antigenic substance or organism. "We also see an induction of the cell cycle marker over infection time when analyzing every cell type individually in particular in the enterocyte lineage (FABP6 and APOA4) (Fig EV2C)." (PMID 34309190, 2021). "Infection also down-regulated genes of the FXR pathway (e.g., NR1H4, FABP6, APOA1, SLC10A2), indicating disruption of the bile acid absorption in ileum." (PMID 26738723, 2016).
adenocarcinoma (1 paper, 2025). A common cancer characterized by the presence of malignant glandular cells. "Caco-2 cells are derived from an immortal adenocarcinoma in which expression of NR1H4 and FABP6 differs from primary colonic epithelial cells." (PMID 40586821, 2025).
FABP6 also shares sentences with these, for which no sentence is quoted: gallstones (3 papers); glioblastoma (2); leukemia (2); acute pancreatitis (1); autoimmune conditions (1); cervical cancer (1); cholelithiasis (1); cholesterol metabolism disorder (1); colon adenocarcinoma (1); colorectal (1); depression (1); Hepatic steatosis (1); intestinal tumors (1); metabolic disease (1); ovarian carcinoma (1); Salmonella Infections (1); Sepsis (1); small cell lung carcinoma (1); type II diabetes (1).